HP (haptoglobin)
Diseases named in the same sentence as HP in open-access papers (continued):
Sharing a sentence is not in itself a finding about the gene and the disease.
cystic tumors (1 paper, 2023). "We detected in the cystic fluid of all tumors some proteins that are already known to play a role in one or more of the cystic tumors studied: gelsolin (GSN), haptoglobin (HP), alpha-2-HS-glycoprotein (AHSG) and alpha-1-antichymotripsin (AACT)." (PMID 37627098, 2023).
delirium (1 paper, 2019). A disorder characterized by confusion; inattentiveness; disorientation; illusions; hallucinations; agitation; and in some instances autonomic nervous system overactivity. "Acute phase proteins (complement c3, fibrinogen and haptoglobin) may be associated with the inflammatory process in delirium." (PMID 30797230, 2019).
endometrial cancer (1 paper, 2024). Primary or metastatic malignant neoplasm involving the endometrium (mucous membrane that lines the endometrial cavity). "Our finding of plasma apolipoproteins and haptoglobin as potential endometrial cancer biomarkers is consistent with previous work." (PMID 38513301, 2024).
epilepsy (1 paper, 2023). A brain disorder characterized by episodes of abnormally increased neuronal discharge resulting in transient episodes of sensory or motor neurological dysfunction, or psychic dysfunction. "The plasma proteomic pattern was assessed, and five major proteins potentially involved in the pathogenesis of epilepsy and elevated Aβ levels were identified: haptoglobin (HP), α2-macroglobulin, ceruloplasmin, complement factor H (CFH), and gelsolin." (PMID 38192726, 2023). "The plasma proteomic pattern was identified, and five major proteins potentially involved in the pathogenesis of epilepsy and control of Aβ levels, including HP, α2-macroglobulin, ceruloplasmin, CFH, and gelsolin, were identified." (PMID 38192726, 2023). "In the current study, HP was significantly upregulated in the epilepsy group compared to that in the healthy control group." (PMID 38192726, 2023). "The findings suggested that haptoglobin, ceruloplasmin, α2-macroglobulin, complement factor H, and gelsolin play roles in canine epilepsy and Aβ levels based on proteomic profiling." (PMID 38192726, 2023).
esophageal cancer (1 paper, 2019). A primary or metastatic malignant neoplasm involving the esophagus. "The purpose of this study was to investigate the type of haptoglobin genotype and its relationship with some nutritional and biochemical risk factors affecting the prevalence of esophageal cancer in patients with early stage esophageal cancer." (PMID 31653132, 2019). "The purpose of this study was to investigate the type of haptoglobin genotype and its relation with some nutritional and biochemical risk factors influencing the prevalence of esophageal cancer in patients with early stage esophageal cancer." (PMID 31653132, 2019). "The results of our study also indicated that there was a significant correlation between haptoglobin genotype and esophageal cancer and that HP1-1 genotype was more prevalent than HP1-2 and HP2-2 genotypes in patients with esophageal cancer." (PMID 31653132, 2019). "In our study, the relationship between esophageal cancer and a specific type of haptoglobin genotype could be very important because this relationship reflects the inherent potential of these individuals to develop esophageal cancer." (PMID 31653132, 2019).
Fulminant hepatic failure (1 paper, 2020). Hepatic failure refers to the inability of the liver to perform its normal synthetic and metabolic functions, which can result in coagulopathy and alteration in the mental status of a previously healthy individual. "In vivo transdifferentiation of hBMSCs in pigs with fulminant hepatic failure confirmed the similarly upregulated expression of 5 hepatogenic genes (TDO2, HP, SERPINA3, LBP and SAA1), showing a 150-fold change in liver tissues at 7 days after hBMSC transplantation." (PMID 32038110, 2020). "Finally, the five genes (TDO2, HP, SERPINA3, LBP and SAA1) validated in hBMSC transplantation with a fulminant hepatic failure (FHF) model in pigs could be potential biomarkers for the characterization of hBMSC-HLCs." (PMID 32038110, 2020).
gallstones (1 paper, 2013). Solid crystalline precipitates in the biliary tract, usually formed in the gallbladder, resulting in the condition of cholelithiasis. "Among the up-regulated proteins in gallstone group or vesicular phase, Immunoglobulin, Alpha-1 acid Glycoprotein and Haptoglobin are considered to be pro-nucleating agents." (PMID 23349907, 2013).
gastric lymphoma (1 paper, 2023). An extranodal lymphoma that arises from the stomach with the bulk of the mass located in the stomach. "Gastric antrum (p < 0.001) and pylorus (p = 0.014) involvement were more common in primary gastric lymphoma patients who were HP-infected, and patients with MALT lymphoma accounted for 56.2% of Hp-infected primary gastric lymphoma patients." (PMID 37183786, 2023).
gingivitis (1 paper, 2025). A disorder involving inflammation of the gums; may affect surrounding and supporting structures of the teeth. "The results of this study indicate that cats with gingivitis have significantly higher concentrations of serum haptoglobin compared with healthy cats, suggesting the presence of an acute inflammatory reaction." (PMID 40944939, 2025). "In the present study, haptoglobin was significantly higher in cats with gingivitis compared with healthy cats, suggesting the presence of an acute‐phase reaction." (PMID 40944939, 2025). "Serum haptoglobin concentration was positively and moderately correlated with the severity of gingivitis." (PMID 40944939, 2025). "• Haptoglobin concentration was significantly increased in cats with gingivitis and correlated with disease severity, suggesting its potential as a biomarker." (PMID 40944939, 2025). "Serum haptoglobin was significantly correlated with the severity of gingivitis, and its role as a prognostic and monitoring tool should be further evaluated." (PMID 40944939, 2025). "Haptoglobin was above the reference interval (RI) (> 3 g/L) in 2/11 (18.2%) of cats with gingivitis, while it was within the RI in all healthy cats." (PMID 40944939, 2025). "Specifically, 2/11 (18.2%) cats with gingivitis had serum haptoglobin in the range of the healthy cats." (PMID 40944939, 2025). "However, further studies are warranted to confirm serum haptoglobin as a monitoring tool for feline gingivitis." (PMID 40944939, 2025). "However, due to the small sample size, it is difficult to draw conclusions about any differences in serum haptoglobin concentrations between cats with varying severities of gingivitis." (PMID 40944939, 2025). "Therefore, the aims of our study were to compare the SAA and haptoglobin concentrations between cats with gingivitis and healthy individuals and to evaluate the correlation of these APPs with the severity of gingivitis." (PMID 40944939, 2025).
glutathione peroxidase deficiency (1 paper, 2011). "Case reports of glutathione peroxidase deficiency leading to excessive hemolysis, low plasma haptoglobin levels leading to hemoglobinuria and erythrocyte membrane-protein anomaly in march hemoglobinuria have been described." (PMID 21982397, 2011).
Granuloma (1 paper, 2017). A compact, organized collection of mature mononuclear phagocytes, which may be but is not necessarily accompanied by accessory features such as necrosis. "In contrast, the necrotic center of a caseous granuloma showed accumulation of transferrin (TF), haptoglobin (HP), and hemopexin (HPX), which are potent extracellular sequesterers of Fe3+, Hb, and heme, respectively." (PMID 28811344, 2017).
gynecologic cancers (1 paper, 2005). "Most notably, the alpha sub-unit of haptoglobin (MW 11.7 kDa) and isoforms of the haptoglobin-1 precursor (HAP1) have been reported to be increased in serum of patients with ovarian and other gynecologic cancers." (PMID 16117833, 2005).
HbH disease (1 paper, 2014). "Decreased levels of haptoglobin were detected in HbH-CS as compared to HbH disease, which suggests that levels of haptoglobin correlate with the severity of HbH disease and could serve as an independent severity predictor in patients." (PMID 25024506, 2014). "This study showed decreased levels of plasma haptoglobin in HbH disease most likely because haptoglobin is degraded and not recycled as part of the reticuloendothelial scavenging system." (PMID 25024506, 2014).
HELLP syndrome (1 paper, 2024). A life-threatening condition that can potentially complicate pregnancy. "However, it is the most-studied parameter in HELLP syndrome, aHUS, and TTP, but other options include total or indirect bilirubin, haptoglobin, and peripheral blood smears." (PMID 38396391, 2024).
hemophagocytic lymphohistiocytosis (1 paper, 2022). "The soluble interleukin-2 receptor alpha chain (sCD25) and the soluble haptoglobin-hemoglobin receptor complex (sCD163) have been used as biomarkers in the diagnosis and surveillance of hemophagocytic lymphohistiocytosis (HLH) activity." (PMID 35329889, 2022).
Hepatosplenomegaly (1 paper, 2024). Simultaneous enlargement of the liver and spleen. "It is known that intravascular hemolysis is characterized by an elevated reticulocyte count and high serum LDH levels, along with low serum haptoglobin, in the absence of hepatosplenomegaly." (PMID 39596172, 2024).
heroin addicts (1 paper, 2014). "The 6 protein spots with an increase upon heroin dependence were identified as immunoglobulin J chain (spots 1 and 2), transthyretin (spot 3 and 7), haptoglobin (spot 4), and vitronectin (spot 6)." (PMID 24743330, 2014). "In addition, we performed haptoglobin (Hp) phenotyping, and showed that the frequency of Hp0 (serum devoid of haptoglobin) was significantly higher in heroin addicts." (PMID 24743330, 2014).
HIV-1 infection (1 paper, 2022). The type species of lentivirus and the etiologic agent of acquired immunodeficiency syndrome (AIDS). "SLC11A1 gene mutations have been associated with increased susceptibility to infectious diseases, as well as diseases of chronic inflammation; however, the iron homeostasis contribution of Nramp1 and haptoglobin during HIV-1 infection remains an area of debate." (PMID 35956266, 2022). "Additional predictors of mortality in HIV-1 infection include genetic polymorphisms in iron regulatory genes, such as the SLC11A1 gene, encoding the natural-resistance-associated macrophage protein-1 (Nramp1), and the HP gene, encoding the free-hemoglobin scavenger haptoglobin." (PMID 35956266, 2022).
hookworm infection (1 paper, 2012). "To determine the association of acute-phase proteins with hookworm infection, we measured the plasma levels of α-2M, CRP, haptoglobin, and SAA in INF and UN individuals." (PMID 23056659, 2012).
Hypercholesterolemia (1 paper, 2015). An increased concentration of cholesterol in the blood. "Six proteins including retinol-binding protein 4 (RBP4), transthyretin (TTR), gelsolin, haptoglobin, complement factor B (CFB) and CD5 antigen-like protein (CD5L) were identified to play imperative roles in lipid metabolism and inflammatory processes as a consequence of hypercholesterolemia." (PMID 27103892, 2015).
hypercortisolism (1 paper, 2024). "Haptoglobin is a moderate acute‐phase protein particularly sensitive to glucocorticoids; elevated concentrations are found both after treatment with glucocorticoids and during naturally occurring hypercortisolism." (PMID 38053513, 2024).
Hyperferritinemia (1 paper, 2025). "Hyperferritinemia with normal haptoglobin levels was associated with higher LRS and FNI, while normal/low ferritin levels and high haptoglobin levels were associated with lower FNI and LRS." (PMID 41010909, 2025).
hypersensitivity pneumonitis (1 paper, 2009). Hypersensitivity pneumonitis (HP) is a pulmonary disease with symptoms of dyspnea and cough resulting from the inhalation of an antigen to which the subject has been previously sensitized. "The IPF and hypersensitivity pneumonitis patients also demonstrated numerous spots corresponding to the N-terminal sequences of haptoglobin." (PMID 19432985, 2009).
idiopathic generalized epilepsies (1 paper, 2008). "Studies have demonstrated an association between the haptoglobin HP2-2 polymorphism and idiopathic generalized epilepsies." (PMID 18554871, 2008). "In addition, haptoglobin expressed by the HP2-2 genotype has the least haemoglobin binding capacity and studies have associated this genotype with idiopathic generalized epilepsy." (PMID 18554871, 2008).
idiopathic nephrotic syndrome (1 paper, 2025). Nephrotic syndrome for which no cause has been identified. "suPAR and haptoglobin have emerged from this systematic review as the most promising biomarkers for the prospective distinction between steroid resistant and steroid sensitive variants of idiopathic nephrotic syndrome." (PMID 39946431, 2025).
IgA vasculitis (1 paper, 2025). "As the present study demonstrates the potential of haptoglobin as a novel biomarker, future multi-center studies are needed to confirm its clinical utility, while mechanistic studies are required to elucidate haptoglobin’s role in the pathogenesis of IgA vasculitis." (PMID 39953336, 2025).
insomnia (1 paper, 2022). A sleep disorder characterized by difficulty in falling asleep and/or remaining asleep. "HP (haptoglobin) is an inflammatory marker whose expression levels are significantly increased in patients with insomnia." (PMID 35958162, 2022). "In the results, HP, FGA, FGG, FGB, and MMP9 were upregulated in patients with insomnia, and FN1, APP, EGF, AHSG, and IGF1 were downregulated compared with controls." (PMID 35958162, 2022). "Among them, HP, MMP9, FGA, FGB, and FGG were validated as upregulated, and APP, AHSG, and IGF1 were downregulated in patients with insomnia." (PMID 35958162, 2022). "The 10 key DEPs screened may be potential targets for insomnia, especially FN1, EGF, HP, and IGF1." (PMID 35958162, 2022).
iron (1 paper, 2017). "A study of 39 patients with T1D patients and 100 controls, found that patients had lower total iron binding capacity, lower transferrin, and higher haptoglobin levels, but found no sign of iron overload." (PMID 29113123, 2017).
larynx cancer (1 paper, 2023). A primary or metastatic malignant neoplasm involving the larynx. "In addition, there was an increased risk of larynx cancer per SD increase in haptoglobin (HR: 1.32; 95%CI: 1.21-1.45) and leukocytes (HR: 1.30; 95%CI: 1.20-1.41)." (PMID 37876941, 2023).
leishmaniasis (1 paper, 2024). Infectious disease that is transmitted through the bite of hematophagous female phlebotomine sand flies. "Finally, APP, such as C-reactive protein and haptoglobin, which could support the monitoring of clinical cases of leishmaniasis, were not evaluated." (PMID 39897361, 2024).
leukaemia (1 paper, 2025). "The interaction between haptoglobin and the immune system is particularly interesting in leukaemia, where immune suppression and altered inflammatory responses contribute to disease progression." (PMID 40606553, 2025).
liver dysfunction (1 paper, 2024). "In relation to non-standard-of-care biomarkers and indices of liver dysfunction, those who died had higher serum hsCRP, serum NT-proBNP, serum AST/ALT, serum haptoglobin, serum hyaluronic acid and serum alpha-2 macroglobulin, but a lower serum, albumin." (PMID 39402659, 2024).
lung adenocarcinoma (1 paper, 2020). A carcinoma that arises from the lung and is characterized by the presence of malignant glandular epithelial cells. "It has been recently reported that Haptoglobin may be a serologic clinical marker to diagnosis lung adenocarcinoma, especially in men." (PMID 32232956, 2020).
lung disease (1 paper, 2011). "In our recent study of BAL fluid proteomics patterns in SM exposed patients we also found that haptoglobin isoforms were significantly elevated in moderate and severe lung disease patients compared to mild and healthy controls." (PMID 21906349, 2011). "One of the main findings was different isoforms of haptoglobin in the plasma of severe lung disease patients but not in healthy controls." (PMID 21906349, 2011). "The results show that α1 haptoglobin isoforms were detected in plasma of the all lung disease patients but none of the healthy controls." (PMID 21906349, 2011).
memory impairment (1 paper, 2022). "The higher serum Cathepsin D, IgE, EGFR, MMP-9, vWF, haptoglobin, and p-Tau181 levels were associated with severity of memory impairment (as indicated by lower MMSE and MoCA scores, and higher ADL, CDRglobal, and CDRsob scores)." (PMID 35769604, 2022).
microcytic anemia (1 paper, 2024). Anemia in which the red blood cell volume is decreased. "These include a normo /macrocytic/microcytic anemia, raised reticulocyte count, raised unconjugated bilirubin, reduced haptoglobin, and blood smear with polychromasia or more specific features, such as spherocytes, schistocytes or agglutination." (PMID 39328644, 2024).
Microscopic hematuria (1 paper, 2018). Microscopic hematuria detected by dipstick or microscopic examination of the urine. "Laboratory findings suggestive of MAHA include elevation in creatinine and LDH, proteinuria, microscopic hematuria, decreased haptoglobin and the presence of reticulocytes." (PMID 29329518, 2018).
motor neuron degeneration (1 paper, 2022). "Myelin oligodendrocyte glycoprotein (MOG), haptoglobin, apolipoprotein C-III (ApoC-III), and apolipoprotein E (ApoE), all failed to recapitulate the motor disability and motor neuron degeneration observed with sALS CSF and ApoB." (PMID 36043141, 2022).
nasal cavity disease (1 paper, 2024). "In this prospective blinded study, canine C-reactive protein (c-CRP), haptoglobin (HPT), and 25-hydroxyvitamin-D (25(OH)D) were investigated for their diagnostic value in 55 dogs with nasal cavity disease (ND)." (PMID 39409857, 2024).
nephritis (1 paper, 2025). Inflammation of renal tissue. "Haptoglobin serum level was elevated in IgAV patients with nephritis or gastrointestinal involvement compared to other IgAV patients." (PMID 39953336, 2025).
normocytic anemia (1 paper, 2025). Anemia in which the red blood cell volume is normal. "It is notable that normocytic anemia with elevated LDH and low haptoglobin levels was a subtle yet critical clue in this diagnostic process." (PMID 40585622, 2025).
osteoarthritis (1 paper, 2022). A noninflammatory degenerative joint disease occurring chiefly in older persons, characterized by degeneration of the articular cartilage, hypertrophy of bone at the margins and changes in the synovial membrane. "Haptoglobin has also been described as elevated in inflammatory, non-immune mediated disease, most notably osteoarthritis and Perthes disease, and was found locally expressed in oncological tissue." (PMID 35964131, 2022).
osteomyelitis (1 paper, 2024). An acute or chronic inflammation of the bone and its structures due to infection with pyogenic bacteria. "Exceptions are osteomyelitis (S. suis), intramammary inoculation of E. coli and swine influenza (H1N1), where SAA, haptoglobin (HP) and CRP, pig major acute phase protein (Pig-MAP) and SAA remained unchanged respectively." (PMID 39237955, 2024).
pancreatic neuroendocrine tumor (1 paper, 2020). Pancreatic endocrine tumor, also known as pancreatic neuroendocrine tumor (PNET), describes a group of endocrine tumors originating in the pancreas that are usually indolent and benign, but may have the potential to be malignant. "TTR and HP bound to fucose have been already proposed as a biomarkers of PDA; CDH5 in pancreatic neuroendocrine tumors developed in Von Hippel–Lindau disease patients and FCGBP in mucinous cysts in the pancreas and PDA." (PMID 32245227, 2020).
peripheral vascular disease (1 paper, 2015). Any disorder affecting blood flow through the veins or arteries outside of the heart. "In this regard, a strong association between the haptoglobin phenotypes and the risk of developing premature coronary and peripheral vascular diseases has been previously reported 36,37." (PMID 26258425, 2015).